ASB15 (ankyrin repeat and SOCS box containing 15)
Description:
May be a substrate-recognition component of a SCF-like ECS (Elongin-Cullin-SOCS-box protein) E3 ubiquitin-protein ligase complex which mediates the ubiquitination and subsequent proteasomal degradation of target proteins.
Synonyms: FLJ43370
Tractability: No criterion of Open Targets' tractability assessment is met for any kind of drug.
Gene: Protein-coding gene on chromosome 7 (123,567,010 to 123,639,481, forward strand). Ensembl gene ENSG00000146809.
Pathways (Reactome):
Immune System: Antigen processing: Ubiquitination & Proteasome degradation
Metabolism of proteins: Neddylation
Gene Ontology:
Molecular function: protein binding
Biological process: intracellular signal transduction; protein ubiquitination
Cellular component: cytosol
Genetic constraint (gnomAD): Loss-of-function variants: 40 observed, 43.91 expected, observed/expected ratio (o/e) 0.91, 90% interval 0.71 to 1.19. The upper end of that interval is the gene's LOEUF score, 1.19, which puts it in group 5 of 6, group 1 being the genes least tolerant of losing a copy. Missense variants: 514 observed, 557.46 expected, observed/expected ratio (o/e) 0.92, 90% interval 0.86 to 0.99. Synonymous variants: 189 observed, 209.27 expected, observed/expected ratio (o/e) 0.9, 90% interval 0.8 to 1.02.
Homologues: Orthologues: chimpanzee ASB15 (99% identical), macaque ASB15 (97% identical), pig ASB15 (93% identical), rabbit ASB15 (92% identical), rat Asb15 (89% identical), mouse Asb15 (88% identical), guinea pig ASB15 (86% identical), tropical clawed frog asb15 (68% identical), zebrafish asb15b (54% identical), zebrafish asb15a (48% identical). Paralogues in human: ASB14 (50% identical), ASB3 (24% identical), ASB10 (18% identical), ASB18 (17% identical), MPHOSPH8 (17% identical), ASB16 (16% identical), ASB4 (15% identical).
Diseases named in the same sentence as ASB15 in open-access papers:
ASB15 is named in the same sentence as 1 disease in open-access papers, as found by Europe PMC text mining. Sharing a sentence is not in itself a finding about the gene and the disease. The quoted sentences say what the papers report.
myeloma (1 paper, 2019). "ASB15 is a component of the ubiquitin–proteasome system (UPS) that has been implicated in deficient DNA repair in myeloma by another UPS protein: USP 45 (ubiquitin specific peptidase 45)." (PMID 31139207, 2019).